Y_RNA (Y RNA )
Gene: Miscellaneous RNA gene on chromosome 14 (72,022,407 to 72,022,516, reverse strand). Ensembl gene ENSG00000200298.
Homologues: Orthologues: chimpanzee Y_RNA (98% identical), macaque Y_RNA (95% identical). Paralogues in human: RNY1 (86% identical), Y_RNA (85% identical), Y_RNA (84% identical), RNY1P11 (83% identical), Y_RNA (83% identical), RNY1P15 (82% identical), Y_RNA (82% identical), Y_RNA (81% identical), RNY1P10 (80% identical), RNY1P5 (80% identical), RNY1P8 (80% identical), Y_RNA (80% identical), and 95 more.